HDAC2 (histone deacetylase 2)
Diseases named in the same sentence as HDAC2 in open-access papers (continued):
Sharing a sentence is not in itself a finding about the gene and the disease.
colorectal cancer (continued). "We found that the states of the nodes canalized by the simultaneous perturbation of MYB, HDAC2, and FOXA2 in the Boolean GRN model were similar to the results from the in vitro knockdown experiments on the various colorectal cancer cell lines." (PMID 39661721, 2025). "We measured transcriptome data of three colorectal cancer cells with scramble knockdown (C) and simultaneous knockdown of MYB, HDAC2, and FOXA2 (KD)." (PMID 39661721, 2025). "Like colorectal cancer cells, endometrial and gastric cancers show frequent MSI and contain subpopulations of cells that lack HDAC2." (PMID 35608750, 2023). "We also demonstrated that MPT0G236 inhibited the activity of Class I HDACs (HDAC1, HDAC2, HDAC3, and HDAC8), as well as of a Class IIb HDAC, HDAC6, leading to the increased acetylation of α-tubulin and histone H3 in both colorectal cancer cells." (PMID 37628767, 2023). "For instance, lncRNA ENSG00000274093.1 was found to promote the combination of histone deacetylase 2 (HDAC2) with histone methyltransferase EZH2 to induce epithelial-mesenchymal transition, thus promoting the migration and invasion of colorectal cancer cells." (PMID 36612282, 2022). "In colorectal cancer, overexpression of HDAC1, HDAC2, and HDAC3 has been found, and HDAC2 expression was identified as an independent survival prognosticator." (PMID 35965507, 2022). "So, we examined lncRNA expression profiles in HDAC2‐RIP, from which we identified and characterized a novel lncRNA, ENSG00000274093.1, which is highly expressed in colorectal cancer tumour tissues." (PMID 33325150, 2021). "The results showed that there was an increase of HDAC2 and an abnormal level of H3K56 acetylation in colorectal cancer tissues." (PMID 33325150, 2021). "Knockdown of either HDAC1 or HDAC2 in liver and colorectal cancer cell lines has little effect on cell viability and proliferation, whereas combined knockdown of HDAC1 and HDAC2 increases cell death and reduces cell proliferation." (PMID 29899862, 2018). "Class-I HDACs consisting of HDAC1, HDAC2, HDAC3 and HDAC8, are well known oncogenic proteins expressed at high levels in malignant cervical and colorectal cancers." (PMID 29190639, 2017). "Additional evidence also supported that HDAC1, HDAC2 and HDAC6 over-expression were observed in the stage III colorectal cancer tissues when compared with normal tissues." (PMID 26087180, 2015). "Once we had made the vectors, we were able to obtain SirT1 KO cells from the colorectal cancer cell line HCT116 and HDAC2 KO cells from the colorectal cancer cell line DLD1." (PMID 23046873, 2012). "In addition, sulforaphane is an HDAC inhibitor used to treat colorectal cancer that can inhibit tumor progression by targeting HDAC1 and HDAC2." (PMID 41513612, 2026). "In HROC50 and HROC53 PDX, the treatment with 5-FU led to an accumulation of HDAC2-negative colorectal cancer cells in the tumor mass that remained after treatment." (PMID 35608750, 2023). "Pulldowns using a lysate of the colorectal cancer cell line SW620 showed clear dose-dependent competition of HDAC1, HDAC2 (including co-competed members of the HDAC1/2 containing CoREST complex), and HDAC6 for both (R/S)-LA and (R/S)-LM with affinities in the range of 3–33 μM." (PMID 37322067, 2023). "Hanigan and colleagues confirmed the existence of HDAC2-negative colorectal cancer cells and that such cells occur in primary human colorectal cancer tissues." (PMID 35608750, 2023). "We show that long-term and short-term cultures of colorectal cancers with MSI contain subpopulations of cells lacking HDAC2." (PMID 35608750, 2023). "Ropero and colleagues reported that RKO cells (from colorectal cancer with MSI) were negative for HDAC2 and insensitive to the HDACi trichostatin-A, which can block all 11 zinc-dependent HDACs." (PMID 35608750, 2023).
colorectal cancer (continued). "This process requires a novel LncRNA, ENSG00000274093.1, which binds to HDAC2 and may act as a modular scaffold for the HDAC1/HDAC2 and EZH2 complexes, thereby altering EMT in colorectal cancer cells." (PMID 33325150, 2021). "Expression of H4K12Ac and HDAC2, but not H3K18Ac, has been found to rise from normal tissue through adenoma to moderately and well-differentiated colorectal carcinoma (CRC), suggesting that HDAC2 and H4K12Ac together may play a role in the progression of colon cancer." (PMID 31121824, 2019). "Thus, our study has identified a novel LncRNA, ENSG00000274093.1, which bound HDAC2, HDAC1 and EZH2, and may act as a modular scaffold of HDAC1/HDAC2 and EZH2 Complexes, and consequently altered EMT of the colorectal cancer cell." (PMID 33325150, 2021). "Interestingly, treatment with a specific inhibitor or siRNA of HDAC3, but not HDAC2, 6, and 8, resulted in obvious upregulation of B7x expression in colorectal cancer cells." (PMID 32934224, 2020). "Additionally, it was previously shown that HDAC2 is overexpressed in colorectal carcinomas but not in the field of the tumor." (PMID 23724067, 2013).
colon carcinoma (39 papers, 2005 to 2025). "The gene encoding HDAC2 has an AT-rich sequence containing 9 adenosine residues in its first exon and 17 to 43% of colon tumors with MSI carry mutations in the gene encoding HDAC2." (PMID 35608750, 2023). "The frameshift mutation in exon 1 of the HDAC2 gene is largely confined to colon tumors with microsatellite instability (MSI), which produces a premature stop codon that results in loss of HDAC2 protein expression." (PMID 33916219, 2021). "In colon cancer cells, HDAC2 expression has been associated with chemoresistance to genotoxic stress." (PMID 26683361, 2016). "This mutation is incredibly common in colon cancer (21%), resulting in a premature stop codon and loss of measurable HDAC2 expression in 83% of mutant tumors." (PMID 24622842, 2014). "Importantly, HDAC2-deficient colon cancer cells are highly refractory to the apoptosis induced by HDAC inhibitors." (PMID 33916219, 2021). "Further, HDAC2 mutations are enriched in MSI colon cancers (43%)." (PMID 24622842, 2014). "Optical microscopy revealed that approximately 30%−40% of HDAC2 KO colon cancer cells displayed pyroptotic morphologies (characteristic ballooning of the cell membrane) after drug treatment, compared to only 3%−6% of wild‐type cells." (PMID 38804602, 2024). "Zhu and colleagues reported that HDAC2 was overexpressed in colon tumor explants and that the oncogenes APC and MYC controlled HDAC2 expression." (PMID 35608750, 2023). "Xenografted patient-derived colon cancer tissues with MSI also show variable patterns of HDAC2 expression in mice." (PMID 35608750, 2023). "The epigenetic modifier histone deacetylase-2 (HDAC2) is frequently dysregulated in colon cancer cells." (PMID 35608750, 2023). "Despite the clear evidence that colon cancers with MSI can exist in HDAC2-proficient and HDAC2-deficient states, surprisingly little is known about the molecular consequences." (PMID 35608750, 2023). "Improved anti-tumour efficacy has also been reported with the potent HDAC2 inhibitor valproic acid (VPA) that supported Ad-replication in colon carcinoma and oncolytic parvovirus in cervical and pancreatic carcinomas." (PMID 35632748, 2022). "HDAC2 expression was found crucial for anti-apoptotic effects and HDAC2 inhibition increased apoptosis in colon carcinoma cells." (PMID 34959719, 2021). "Previous studies have shown that knockdown of either HDAC1 or HDAC2 resulted in the sensitization of chronic lymphocytic leukemia cells to Trail-induced apoptosis and a reduction in the proliferation of colon cancer cells." (PMID 30669676, 2019). "It has recently been reported that USP4 directly interacts and de-ubiquitinates HDAC2 resulting in its stability in colon cancer cells." (PMID 30071870, 2018). "Among all the HDACs of class 1, HDAC2 is overexpressed in colon cancer tissues (81.9%) compared to normal colon tissue (53.1%)." (PMID 29190639, 2017). "Since HDAC2-dependent NF-κB activity protects colon cancer cells from genotoxic stress, our data also suggest that high HDAC2 levels, which are frequently found in tumors, are linked to chemoresistance." (PMID 25704882, 2015). "It islikely, therefore, that the high levels of ARF and HDAC2 enhance the potency of the HUWE1 inhibitorsin colon cancer cells and contribute to the specificity of the effects." (PMID 25253726, 2014). "A previous study demonstrated that the increased HDAC2 expression was found in colon cancer, and the induction of HDAC2 was dependent on Wnt pathway and c-Myc." (PMID 22132221, 2011).
colon carcinoma (continued). "Our recent publications have shown that AA colon tumors display an aberrant global histone (H3, and H4) acetylation and HDAC2 expression." (PMID 19750230, 2009). "A recent report showed that elevated HDAC2 mRNA expression was observed in 82% of 57 human colonic cancer patients." (PMID 15756260, 2005). "In detail, HDAC2 was demonstrated to inhibit H19 expression in colon carcinoma." (PMID 40885718, 2025). "Overexpression of HDAC2 was recently reported in colon cancer." (PMID 16638127, 2006). "In the light of our findings, we propose such a model that upregulated PSEN1 in colon cancer might facilitate PD-L1 truncation via potential proteolytic processing, releasing its active C-terminal fragment which is subject to HDAC2-mediated deacetylation and subsequent nuclear translocation." (PMID 36059511, 2022). "Previous studies demonstrated that inhibition of HDAC2 and HDAC3 increased p21 expression in human colon cancer." (PMID 39273544, 2024). "The histone deacetylase 2 (HDAC2), an enzyme involved in gene regulation, is a potent drug target for the treatment of colon cancer." (PMID 39037973, 2024). "HDAC2 is enhanced in liposarcoma, and Ohio State University HDAC42 (OSU-HDAC42) is a selective HDAC2 inhibitor that has been examined in colon cancer." (PMID 35008848, 2021). "Several studies have demonstrated increased expression of the class-I HDACs: HDAC1, HDAC2, and HDAC3, in multiple human cancers, including colon cancer." (PMID 29152115, 2017). "Notably, treatment with SCA, a selective HDAC2 inhibitor, induced a dose‐dependent upregulation of NLRP3 levels in colon cancer cells." (PMID 38804602, 2024). "This suggests that unlike in colon cancer, transcriptional deregulation of HDAC2 in liver cancer is not affected by Wnt pathway." (PMID 22132221, 2011). "Furthermore, we observed that HDAC2 up-regulation is one of the earliest events in CRC carcinogenesis and observed this in human field carcinogenesis, the azoxymethane-treated rat model, and in more aggressive colon cancer cell lines." (PMID 23724067, 2013). "Nonetheless, our results are consistent with recent observations in HCT116 colon cancer cells, where HDACI treatment or depletion of HDAC2, but not HDAC1, sensitizes towards TNFα-induced apoptosis." (PMID 20398369, 2010).
cardiac hypertrophy (37 papers, 2013 to 2025). "Further investigations are warranted to elucidate the specific mechanisms underlying the involvement of S1P and HDAC2 in cardiac hypertrophy through the modulation of HDAC2 activity." (PMID 40497340, 2025). "HDAC2 deficiency attenuates cardiac hypertrophy in mice by increasing the transcription of the gene encoding phosphatidylinositide phosphatase SAC2." (PMID 35264952, 2022). "The increased level of class I HDACs, particularly HDAC2, was directly related to the cardiac hypertrophy or caused fatal cardiac arrhythmias." (PMID 34884505, 2021). "Previously, we clearly reported that the PCAF causes cardiac hypertrophy by inducing the acetylation of HDAC2 K74." (PMID 34576109, 2021). "Among them, HDAC2 stimulates cardiac hypertrophy, whereas HDAC3 causes myocyte hyperplasia during embryonic and fetal life." (PMID 33959033, 2021). "When these HDAC2-deficient survivors were exposed to hypertrophic stimuli, cardiac hypertrophy and fibrosis were attenuated, indicating a detrimental role of HDAC2 upon pathophysiological conditions." (PMID 24310814, 2014). "Additionally, HDAC2 expression is significantly increased in right ventricular tissue, which causes cardiac hypertrophy." (PMID 40497340, 2025). "Research has found that acetylation and phosphorylation of HDAC2 are linked to cardiac hypertrophy." (PMID 40497340, 2025). "Indeed, as previous study suggested that S394 is responsible for the cardiac hypertrophy-associated activation of HDAC2." (PMID 37312162, 2023). "Furthermore, HDAC2 deficiency attenuated cardiac hypertrophy, whereas hypertrophy was augmented in HDAC2 transgenic mice." (PMID 33959033, 2021). "In addition, over-expression of HDAC2 had augmented hypertrophy, but HDAC2 deficiency prevented attenuated cardiac hypertrophy." (PMID 30134825, 2018). "Our data further showed that Asb10 prevents HSP70 from undergoing STUB1-mediated ubiquitination and degradation, and HSP70-associated cardiac inflammation and HDAC2 phosphorylation may contribute to Asb10 overexpression-induced pathological cardiac hypertrophy and heart failure." (PMID 40399264, 2025). "In PPP2CA transgenic mice, cardiac hypertrophy and fibrosis from isoproterenol are minimal, but HDAC2 S394E expression induces hypertrophy." (PMID 40660005, 2025). "Taken together, HDAC2 phosphorylation constitutes a pivotal upstream regulatory mechanism driving the pathogenesis of cardiac hypertrophy." (PMID 40497340, 2025). "The activity of HDAC2 is inhibited by MICAL3 through self-generated ROS; therefore, in myocardial hypertrophy, the positive regulation of HDAC2 is inhibited, and the hypertrophy of myocardial cells is inhibited." (PMID 40660005, 2025). "In the isoproterenol (ISO)-induced rat model of myocardial hypertrophy, palmatine treatment groups (25 mg/kg and 50 mg/kg) selectively suppressed histone deacetylase histone Deacetylase 2 (HDAC2) expression compared to the model group." (PMID 40786032, 2025). "Phosphorylation-induced redistribution of HDACs is essential for their function, with HDAC2 becoming activated during cardiac hypertrophy progression." (PMID 40660005, 2025). "HDAC inhibitors suppress cardiac hypertrophy by modulating the activity of Kruppel‐like factor 4 (KLF4), which plays a crucial role in the HDAC2‐mediated activation of foetal gene expression associated with hypertrophy under hypertrophic stress." (PMID 40497340, 2025). "A previous study found that BRG1 attenuated exercise-induced physiological myocardial hypertrophy by inhibiting pressure overload-induced histone deacetylase 2 activation and serine/threonine kinase/glycogen synthase kinase 3β phosphorylation." (PMID 38867118, 2025). "HDAC2 inhibition is a novel therapeutic strategy to prevent cardiac hypertrophy‐related electrophysiological remodelling." (PMID 40497340, 2025).
cardiac hypertrophy (continued). "In contrast, transgenic overexpressing HDAC2 in cardiomyocytes led to cardiac hypertrophy, indicating that HDAC2 is both necessary and sufficient for hypertrophic responses." (PMID 38983721, 2024). "The protective effect of CK2 on cardiac hypertrophy is mediated by regulation of the phosphorylation of histone deacetylase 2 (HDAC2)." (PMID 37507372, 2023). "HDAC2 seems to induce cardiac hypertrophy by increasing the Akt signaling pathway, which is involved both in cardiac hypertrophy and in the maintenance or improvement of cardiac functions." (PMID 37686073, 2023). "BRG1 can also activate the stress overload-induced 3β pathway by inhibiting Hdac2, affecting cardiac hypertrophy and fibrosis." (PMID 37759781, 2023). "HDAC2 reduction in mice resulted in less sensitivity to hypertrophic stimuli, whereas the mice with Hdac2 overexpression developed cardiac hypertrophy." (PMID 36523510, 2022). "Specifically, histone deacetylase 2 (HDAC2) can result in severe cardiac hypertrophy, while HDAC2 knockout mice are resistant to exogenous hypertrophy stimulation." (PMID 36186970, 2022). "Mhrt779 inhibited the activation of the histone deacetylase 2 (HDAC2)/Akt/GSK3β pathway during pathological cardiac hypertrophy." (PMID 35461308, 2022). "For example, SK-7041, a highly selective inhibitor of HDAC1 and HDAC2, alleviated cardiac hypertrophy in the rat TAC model." (PMID 35126818, 2022). "The enzymatic activity of HDAC2 was reported to be critical for the development of cardiac hypertrophy, whereas upregulation of HDAC8 expression was critical for promoting cardiac hypertrophy." (PMID 35126818, 2022). "Among class I HDACs, HDAC2 has been best characterized for its role in the modulation of cardiac hypertrophy." (PMID 35126818, 2022). "The acetylation of HDAC2 is required for the sequential phosphorylation of HDAC2 S394, a hypertrophy-responsive phosphorylation residue of HDAC2, which then activates HDAC2 for the initiation of cardiac hypertrophy." (PMID 34576109, 2021). "Here we present novel findings demonstrating that, besides HDAC2, HDAC8 is directly implicated in cardiac hypertrophy." (PMID 33959033, 2021). "We previously reported that histone deacetylase 2 (HDAC2) promotes the development of cardiac hypertrophy, and its activity is tightly regulated by casein kinase 2α1-mediated phosphorylation." (PMID 34576109, 2021). "Among the 18 mammalian HDACs, HDAC2 acts as a pro-hypertrophic regulator of cardiac hypertrophy development by modulating the GSK3β or kruppёl like factor 4 activity." (PMID 33959033, 2021). "We previously reported that HDAC2 directly induced cardiac hypertrophy and activated heat shock protein 70 (HSP70) in heart tissues." (PMID 33959033, 2021). "In previous research, Akt has been shown to be a downstream protein of HDAC2 that is positively regulated by HDAC2 in isoproterenol-induced cardiac hypertrophy." (PMID 34322124, 2021). "Taken together, our results suggest that PP2A is a critical regulator of HDAC2 activity and pathological cardiac hypertrophy and is a promising target for future therapeutic interventions." (PMID 30050113, 2018). "Taken together, our results suggest that PP2A acts as an endogenous phosphatase and an inhibitor of HDAC2 in the development of cardiac hypertrophy." (PMID 30050113, 2018). "PPP2CA transgenic mice were protected against isoproterenol-induced cardiac hypertrophy and subsequent cardiac fibrosis, whereas simultaneous expression of HDAC2 S394E in the heart did induce hypertrophy." (PMID 30050113, 2018). "Here, we propose a novel mechanism for the regulation of HDAC2 phosphorylation status and its activity in the development of cardiac hypertrophy." (PMID 30050113, 2018). "For example, HDAC2 promotes cardiac hypertrophy, and cardiac-specific deletion of HDAC3 in mice leads to cardiac hypertrophy and excessive myocardial lipid accumulation." (PMID 30115891, 2018).